CD200 (CD200 molecule)
Diseases named in the same sentence as CD200 in open-access papers (continued):
Sharing a sentence is not in itself a finding about the gene and the disease.
breast carcinoma (continued). "In this study, we identified CD200 and CD276, respectively, as candidate innate and adaptive immune checkpoints in breast cancer stem cells." (PMID 33932112, 2021). "Our study suggested that CD200 and CD276 are candidate inhibitory immune checkpoints in breast cancer stem cells, which are potentially regulated by Wnt, TGF‐β, and Hedgehog signaling." (PMID 33932112, 2021). "We also identified gene signatures that represent Wnt, TGF‐β, and Hedgehog signaling‐related CD200 and CD276 expression in breast cancer stem cells." (PMID 33932112, 2021). "Taken together, we considered CD200 and CD276, respectively, as potential innate and adaptive immune checkpoints in breast cancer stem cells." (PMID 33932112, 2021). "Most recent studies confirmed the increase in chemotherapy activity within the synergy of CD200 (or CD200R) blockade to cure and to produce immune resistance to metastasis of metastatic breast cancer in mice models." (PMID 30800162, 2019). "Altered interaction between CD200 and CD200R represents an example of “checkpoint blockade” disrupting an effective, tumor‐directed, host response in murine breast cancer cells." (PMID 26725371, 2016). "CD200 mRNA expression is reportedly higher in bone, lung, and liver metastatic tissues from patients with aggressive breast cancer than in adjacent noncancerous breast tissues from those with non-metastatic breast cancer." (PMID 37894750, 2023). "The innate immune checkpoint CD200 and the adaptive immune checkpoint CD276, respectively, exhibited a strong correlation with basal/stem gene signature and invasiveness gene signature, both of which represent breast cancer stem cells." (PMID 33932112, 2021). "In summary, our study revealed that CD200 and CD276 may act as cancer stem cell–specific immune checkpoints to mediate immune resistance in breast cancer." (PMID 33932112, 2021). "Moreover, we identified gene signatures that represent Wnt, TGF‐β, and Hedgehog signaling‐related CD200 and CD276 expression in breast cancer stem cells." (PMID 33932112, 2021). "Therefore, Wnt, TGF‐β, and Hedgehog signaling are potentially the main pathways regulating the inhibitory immune checkpoints CD200 and CD276 in breast cancer stem cells." (PMID 33932112, 2021). "Our results suggested that cancer stem cell–specific CD200 and CD276 might inhibit the surveillance of innate and adaptive immune system in luminal A breast cancer, thus contributing to poor survival." (PMID 33932112, 2021). "CD200 expression was found to have no strong correlation with the other immune checkpoints expressed by breast cancer cells, and neither was CD276 expression." (PMID 33932112, 2021). "As breast cancers can be classified into basal/stem cell–enriched and luminal/differentiated cell‐enriched clusters, we used logistic regression to screen out gene signatures which indicate Wnt, TGF‐β, and Hedgehog signaling‐related CD200 and CD276 in breast cancer stem cells." (PMID 33932112, 2021). "Possible therapeutic value of CD200 fusion protein (CD200fc) was not previously studied in an aggressive breast carcinoma model under in-vivo condition." (PMID 29721190, 2018). "To test if our antagonist was efficacious in a non-CNS tumor, we tested multiple CD200 antagonists on our breast carcinoma model." (PMID 25598973, 2014). "Finally, we validated the expression level of immune-related genes in breast cancer patients-derived cardiomyocytes with doxorubicin-induced cardiotoxicity and found that the level of RAD9A, HSPA1B, GATA2, IGF2R, CD200, ERCC8, and BCL11A genes are consistently dysregulated." (PMID 37684436, 2023). "In a 4THM breast carcinoma murine model, CD200 overexpression in CD200 transgenic and CD200R1 knockout BALB/c mice was correlated with the complete regression of primary tumors in 3/7 CD200 transgenic mice and attenuated visceral metastasis to the lungs and liver." (PMID 38137547, 2023).
breast carcinoma (continued). "Finally, we validated that RAD9A, HSPA1B, GATA2, IGF2R, CD200, ERCC8, and BCL11A genes are consistently dysregulated in the doxorubicin-induced human-induced pluripotent stem cell-derived cardiomyocytes (hiPSC-CMs) derived from breast cancer patients." (PMID 37684436, 2023). "Besides some published potential biomarkers of breast cancer bone metastasis were identified in our study, we also detected some novel biomarkers or their relationship with breast cancer bone metastasis has never been reported, such as TNFAIP6, DHRS3, ASS1, RIPK4, VIM, CD200." (PMID 30918839, 2019). "For instance, 4THM breast cancer cell growth and invasion were increased in CR200R1KO mice and decreased in mice over-expressing CD200, with a lack of CD200R1 expression related to decreased CD8+ and CD3+CD25+ T cells." (PMID 32635224, 2020). "In the studies described herein, we used our own CD200-/- BALB/c mice and WT BALB/c mice as EMT6 and EMT6siCD200 tumor bearing hosts to investigate how the lack of CD200 expression by host and tumor cells affected EMT6 breast cancer progression." (PMID 28234914, 2017). "However, more convincing evidence of CD200 and CD276 expressed in human breast cancer stem cells has not been provided." (PMID 33932112, 2021). "Using a transplantable EMT6 mouse breast cancer line CD200 expression, by tumor cells or host, increased local tumor growth and metastasis to DLN, which was abolished by neutralizing antibody to CD200, or following growth in mice lacking the primary inhibitory receptor for CD200 (CD200R1KO mice)." (PMID 25409195, 2014). "While the direct interactions between CD200 and CDK4/6 pathways are not well documented, the preclinical evidence suggests that the immune modulation from anti-CD200 might potentiate the effects of CDK4/6 inhibitors in hormone receptor-positive, HER2-negative breast cancers." (PMID 39795972, 2024).
chronic lymphocytic leukemia (32 papers, 2012 to 2025). "CD200 is expressed in a number of malignancies and has been associated with poor outcome, including melanoma, acute myeloid leukemia, multiple myeloma, chronic lymphocytic leukemia, renal carcinoma, bladder cancer, ovarian carcinoma, and colon carcinoma." (PMID 36074574, 2022). "In conclusion, CD200 is an accurate diagnostic marker for chronic lymphocytic leukemia, and can refine the modified Matutes score accuracy when added with other markers." (PMID 33606850, 2021). "In studies of chronic lymphocytic leukemia (CLL) interactions between CD200:CD200R were found to be associated with unfavorable prognosis." (PMID 33562512, 2021). "The findings of a clinical trial conducted on chronic lymphocyte leukemia patients revealed that the expression level of CD200 was diminished after receiving of ibrutinib." (PMID 40469777, 2025). "This led to the development of samalizumab (ALXN6000), a first-in-class anti-CD200 antibody tested in phase I clinical trials for multiple myeloma and chronic lymphocytic leukaemia by Alexion Pharmaceuticals." (PMID 37082107, 2023). "In the extracellular space, ADAM28-mediated CD200 ectodomain shedding leads to increased serum levels of a biologically-active, soluble CD200 ectodomain fragment in B-cell CLL patients." (PMID 36738455, 2023). "This study aimed at investigating the prognostic significance of the soluble form of CD200 antigen evaluated at diagnosis in patients with chronic lymphocytic leukemia (CLL)." (PMID 34439393, 2021). "All chronic lymphocytic leukemia cases and 20 of 53 (37.7%) of other B-chronic lymphoproliferative disorders demonstrated high CD200 expression (≥30%)." (PMID 33606850, 2021). "This first-in-human study investigated the therapeutic use of samalizumab as a CD200 immune checkpoint inhibitor in chronic lymphocytic leukemia (CLL) and multiple myeloma (MM)." (PMID 31443741, 2019). "In hematological malignancies CD200 expression was first reported in chronic lymphocytic leukemia, where it has a role in differential diagnosis with mantle cell lymphoma." (PMID 26338961, 2015). "Anti-CD200 antibodies have demonstrated in vitro efficacy and are under investigation in chronic lymphocytic leukemia." (PMID 26338961, 2015). "CD200 is a new marker that was found to be up-regulated in chronic lymphocytic leukemia (CLL)/small lymphocytic lymphoma (SLL) when compared with normal B cells by flow cytometry immunophenotyping." (PMID 31803290, 2012). "Blockade of CD200 immune checkpoint has also been explored in a clinical trial phase 1 with samalizumab, a recombinant humanized monoclonal antibody that targets CD200, in relapsed or refractory B-cell chronic lymphocytic leukemia and multiple myeloma." (PMID 38455039, 2024). "Clinical and in vitro studies reinforce this assertion as the administration of an anti-CD200 monoclonal antibody to block CD200/CD200R signaling was shown to be sufficient in reducing Treg frequencies for chronic lymphocytic leukemia patients and cell samples." (PMID 38137547, 2023). "Recently, CD200 is considered as a relatively consistent marker in chronic lymphocytic leukemia." (PMID 33606850, 2021). "Also, CD200 addition to the Matutes score has correctly recognized all 199 chronic lymphocytic leukemia cases including 10 atypical chronic lymphocytic leukemia cases." (PMID 33606850, 2021). "Importantly, CD200 is expressed in a wide spectrum of cancers, including chronic lymphocytic leukemia (CLL), multiple myeloma, acute myeloid leukemia, melanoma, ovarian tumors, metastatic small cell carcinoma, and glioblastoma." (PMID 30682795, 2019). "CD200 has been shown to be overexpressed in chronic lymphocytic leukemia (CLL)." (PMID 26910908, 2016). "In addition, anti-CD200 demonstrated efficacy in a B-cell chronic lymphocytic leukemia that led to the use in a clinical trial (clinicaltrials.gov identifier NCT00648739)." (PMID 25598973, 2014).
chronic lymphocytic leukemia (continued). "Pallasch and colleagues demonstrated that antagonistic anti-CD200 antibody could promote chronic lymphocytic leukemia cell-induced proliferation of antigen-specific T cells and reduce the proportion of CD4+CD25highFoxP3+ cells." (PMID 22621248, 2012). "Moreover, CD200R activation could result in tumor progression, and silencing CD200 with an antibody or siRNA could enhance T-cell function in patients with Chronic lymphocytic leukemia, CLL." (PMID 38780647, 2024). "In fact, CD200 is particularly helpful in distinguishing some disease entities, such as chronic lymphocytic leukemia (CLL) and mantle cell lymphoma (MCL), whose clinical behavior and prognosis is quite different." (PMID 34439393, 2021). "CD200 is overexpressed in a wide variety of solid and hematological tumor cell types, including chronic lymphocytic leukemia (CLL) multiple myeloma (MM), acute myeloid leukemia (AML) and others, and is also expressed at elevated levels on cancer stem cells." (PMID 31443741, 2019). "We have previously reported the existence of a soluble form of CD200 (sCD200) in human plasma, and found sCD200 to be elevated in the plasma of Chronic Lymphocytic Leukemia (CLL) patients." (PMID 27111430, 2016). "The expression of CD200 in hematologic malignancies was first reported for chronic lymphocytic leukemia (CLL)." (PMID 31803290, 2012). "This study compares immune factors like PD-1/PD-L1, CTLA-4/CD86, CD200R/CD200, and EBV in chronic lymphocytic leukemia (CLL, a SID) and common variable immunodeficiency (CVID, a PID)." (PMID 37835480, 2023). "Membrane-bound CD200 is overexpressed in chronic lymphocytic leukemia (CLL), and there is some evidence that its soluble ectodomain (sCD200) could also be involved in the pathophysiology and the disease." (PMID 34439393, 2021). "Isolated antibodies were found to target six different receptors on Chronic Lymphocytic Leukemia cells; CD21, CD23, CD32, CD72, CD200, and HLA-DR of which CD32, CD200, and HLA-DR appeared as the most potent targets for antibody-based cytotoxicity treatment." (PMID 30182064, 2018). "For instance, in a cross-sectional study of 67 patients with mature B cell lymphoproliferative disorders, high levels of CD200 expression were correlated with advanced stage on the Rai and Binet staging systems along with earlier time to progression in CLL (Chronic Lymphocytic Leukemia) patients." (PMID 38137547, 2023). "A growing body of evidence indicates that the therapeutic application of anti-CD200 treatment could potentially provide benefits in CD200-overexpressing malignancies encompassing hematopoietic tumors, such as chronic lymphocytic leukemia (CLL), as well as multiple solid tumors." (PMID 37894750, 2023). "CD200 expression can be observed in various hematopoietic cancers, including acute myeloid leukemia (AML), as well as in certain diseases derived from B lymphocytes, such as chronic lymphocytic leukemia (CLL) and hairy cell leukemia (HCL)." (PMID 37894750, 2023). "Chronic lymphocytic leukemia is the most common leukemia (CLL) in the adult Western population, and is characterized by the proliferation of clonal B lymphocytes expressing CD5, CD23 and CD200." (PMID 36661671, 2022). "In humans, the anti-CD200 mAb Samalizumab has entered two phase I clinical trials: one on patients bearing solid tumors (NCT02987504) and the other on patients with B-cell chronic lymphocytic leukemia (B-CLL) or multiple myeloma (NCT00648739) (clinicaltrials.gov)." (PMID 32656079, 2020). "Overexpression of CD200 has been reported in chronic lymphocytic leukemia (CLL) and hairy cell leukemia but not in mantle cell lymphoma, thus helping to better discriminate between these different B cell malignancies with different prognosis." (PMID 33324560, 2020). "The search comprised the terms “CD200”, “chronic lymphocytic leukemia”, and “chronic B cell leukemias” without a date restriction." (PMID 33324560, 2020).
chronic lymphocytic leukemia (continued). "The negative CD5, CD23, and CD200 may exclude the diagnosis of chronic lymphocytic leukemia/small cell lymphoma, and the negative CD5, Cyclin D1, FMC7, and SOX-11 can exclude the possibility of mantle cell lymphoma." (PMID 38335376, 2024).
melanoma (28 papers, 2009 to 2025). A malignant, usually aggressive tumor composed of atypical, neoplastic melanocytes. "In metastatic melanoma, CD200 is regulated by ERK activation downstream of N-RAS or B-RAF mutations suggesting that CD200 induction is an early event in melanoma pathogenesis." (PMID 36738455, 2023). "High expression of CD200 is associated with progression from nevi to melanoma and its expression is further increased in melanocytic lesions." (PMID 33562512, 2021). "CD200, a type I membrane-associated glycoprotein and member of the immunoglobulin superfamily is highly expressed on melanoma cells and was found to be regulated by ERK activation." (PMID 24194739, 2013). "Expression of CD200 has been implicated in a variety of human cancer cells including melanoma cells and has been thought to play a protumor role." (PMID 22319630, 2012). "Expression of CD200 has been implicated in a variety of human cancer cells including melanoma cells and has been reported to play protumor effects via inhibiting tumor immunity." (PMID 22319630, 2012). "In melanoma and other cancers, CD200 overexpression has been linked to immune evasion." (PMID 40075669, 2025). "Moreover, in CD200R-deficient mice that were implanted with B16-CD200 melanoma cells, enhanced growth of CD200+ tumors was observed along with metastasis to the liver, lungs, kidneys, and peritoneal cavity." (PMID 38137547, 2023). "Thus, we investigated the effects of CD200 deficiency on the systemic development of mouse melanoma B16F10 cells." (PMID 30653571, 2019). "In contrast, we showed that CD200-deficiency did decrease melanoma tumor burden." (PMID 30653571, 2019). "A previous study using B16 melanoma and J558 plasmacytoma mouse syngeneic models found that CD200 expression could inhibit tumor growth and metastasis by shaping the TME, while another indicated that CD200R1-deficient mice display accelerated CD200+ B16 melanoma growth." (PMID 32635224, 2020). "Elevated CD200 expression often correlates with worse prognosis and increased metastatic potential in melanoma." (PMID 40075669, 2025). "In a B16 melanoma model, inoculation with CD200-positive B16 melanoma cells inhibited tumor formation and growth in C57BL/6 mice and significantly reduced the formation of metastatic foci in the lungs." (PMID 40534859, 2025). "In contrast, and as reported by many others, CD200-deficiency decreased melanoma tumor burden, while both endogenous or tumor-expressed CD200 restored the growth of metastatic melanoma foci." (PMID 38540350, 2024). "They concluded that these studies should prompt caution in using the blockade of CD200 as an immunotherapy for melanoma." (PMID 38540350, 2024). "In melanoma cells, CD200 can inhibit Th1 cytokine production and, in CLL, cytotoxic T cell proliferation." (PMID 36738455, 2023). "Research has shown that the infiltration of CD200 + cytotoxic T cells in malignant tumors such as melanoma and esophageal cancer can help improve the patient response rate to PD-1/PD-L1 therapy and prolong survival." (PMID 37978247, 2023). "High levels of CD200 have been found to be expressed on various types of human cancer cells, including hairy cell leukemia, acute myeloid leukemia, malignant melanoma, CLL, multiple myeloma, testicular cancer, renal carcinoma, colon carcinoma, and GBM." (PMID 36756156, 2023). "In a B16 melanoma study, inoculation with CD200+ B16 melanoma cells disrupted tumor formation and growth in C57BL/6 mice and significantly reduced metastatic tumor foci formation in the lungs." (PMID 38137547, 2023). "This has been supported by previous studies which have discovered that high levels of CD200 were expressed on an array of cancer cells, including but not limited to various leukemias, malignant melanoma, and several neuroendocrine cancers." (PMID 36756156, 2023).